DOCK3 (dedicator of cytokinesis 3)
Diseases named in the same sentence as DOCK3 in open-access papers (continued):
Sharing a sentence is not in itself a finding about the gene and the disease.
cancer (9 papers, 2013 to 2025). A tumor composed of atypical neoplastic, often pleomorphic cells that invade other tissues. "This inhibition of phosphorylation impairs Dock3 expression, and since Dock3 inhibits β-catenin and induces WAVE2 expression (WAVE2 inhibits cell movement), the lack of Dock3 expression causes cancer migration." (PMID 37016434, 2023). "Moreover, multiple studies reported DOCK3 to be implicated in cancer cell invasion and migration (as recently reviewed)." (PMID 29228715, 2017). "Recent studies have highlighted the importance of several key genes and molecular pathways, including Dedicator of Cytokinesis 3 (DOCK3), in tumor progression and therapeutic response, drawing attention to the potential role of DOCK3 in various cancers." (PMID 41200217, 2025). "The DOCK3 gene has been reported to participate in various processes related to invasion, migration, and metastasis in cancer cells." (PMID 37214090, 2023). "Probing of DOCK3 expression in cancer and other atlas databases (e.g., The Cancer Genome Atlas—TCGA) may yield insights into DOCK3 dysregulation in disease contexts." (PMID 37895289, 2023). "To date, the antiapoptotic genes OLFM4, SIRT1, PIM-1, and DOCK3, the tumor suppressor PTEN, the cell proliferation and invasion genes CITRON and CLDN10, and FGF9 expressed by cancer-associated fibroblasts have been reported as potential targets for miR-486/miR-486-5p in malignant disease." (PMID 26895105, 2016). "DOCK3 is a member of the DOCK family of guanine nucleotide exchange factors (GEFs), which interacts with other cancer-related signaling pathways, such as the actin cytoskeleton and focal adhesion pathways, playing a critical role in regulating cytoskeletal dynamics." (PMID 41200217, 2025). "Dock3 in conjunction with NEDD9 promotes EMT, mesenchymal migration and metastasis of cancer cells." (PMID 23441967, 2013). "Although it is not desirable to fully activate RAC1 in every tissue due to its role as a known cancer-driving oncogenic factor, temporal and tissue-specific modulation of active RAC1 may be beneficial for rescuing some of the DOCK3-affected pathways that are altered in patients." (PMID 37895289, 2023). "All these results indicate that DOCK3 regulates cytoskeleton rearrangement mainly via its GEF activity, however, whether DOCK3 could regulate cell movement independent of its GEF activity and its regulation in cancer cells are mainly unknown." (PMID 26716413, 2016).
tumor (5 papers, 2016 to 2025). "Its tumor-specific expression and association with aggressive clinical features nominate DOCK3 as a novel biomarker for risk stratification and a promising therapeutic target for combinatorial immunotherapy in immunologically “cold” PCa." (PMID 41200217, 2025). "In the tumor microenvironment, elevated DOCK3 expression was associated with a significant increase in cytotoxic immune infiltration, notably of CD8+ T and Natural Killer cells, a finding consistently supported by multiple computational algorithms (all p<0.05)." (PMID 41200217, 2025). "DOCK3 expression was found to be significantly elevated in metastatic (M1) tumors compared to primary (M0) tumors (p<0.05) and demonstrated a strong positive correlation with a higher tumor mutational burden (TMB) in metastatic samples (p<0.001)." (PMID 41200217, 2025). "In small cell lung cancer, DOCK3 mediates tumor cell adhesion, migration, and invasion through activating the RAC1 signaling pathway." (PMID 41200217, 2025). "Elevated DOCK3 expression correlates with both tumor aggressiveness and increased infiltration of cytotoxic immune cells, suggesting a dual role in promoting tumor progression while shaping the immune landscape." (PMID 41200217, 2025). "Co-expression with known tumor markers (e.g., KLK3, MMP9) reinforces DOCK3’s tumor-specific expression signature." (PMID 41200217, 2025). "High DOCK3 expression showed a significant positive correlation with tumor samples (compared to normal tissue) and metastatic status (p < 0.01), suggesting a role in tumorigenesis and dissemination." (PMID 41200217, 2025). "This study investigates DOCK3’s role in PCa metastasis and tumor immune microenvironment (TIME) remodeling." (PMID 41200217, 2025). "High DOCK3 expression correlated with an activated tumor immune microenvironment, suggesting its potential as a therapeutic target for PCa immunotherapy." (PMID 41200217, 2025). "By regulating cell movement and actin dynamics, DOCK3 can facilitate tumor cell invasion and metastasis." (PMID 41200217, 2025). "Research demonstrated that DOCK3, which is typically expressed in neural tissues, also plays a significant role in immune cells like T cells and macrophages, impacting their ability to migrate and respond to tumor cells." (PMID 41200217, 2025). "However, the role of DOCK3 in PCa metastasis and its regulatory mechanisms in the tumor immune microenvironment remain to be further elucidated." (PMID 41200217, 2025). "It is plausible that DOCK3-driven structural changes in the tumor architecture enhance immune cell recruitment, or alternatively, DOCK3 may be involved in immune-editing processes that support immune evasion despite apparent infiltration." (PMID 41200217, 2025). "Additionally, we will evaluate the correlation between DOCK3 expression levels and clinical features such as Gleason score and tumor stage, providing theoretical support for the development of DOCK3-based prognostic biomarkers." (PMID 41200217, 2025). "Furthermore, proteins in the myogenesis (Pax7/MyoD/MyoG) and myofiber survival (Dock3/Pten/Akt) networks, which are regulated by and/or regulate miR-486, are deregulated in skeletal muscles of tumor-bearing transgenic mice compared to controls." (PMID 31941005, 2020). "Additionally, tools like cellphoneDB could be employed in the future to explore DOCK3-mediated cell-cell communication networks, offering deeper insights into its role in immune modulation and tumor progression." (PMID 41200217, 2025). "In addition, DOCK3 inhibited lamellipodium dynamics and tumor cell movement." (PMID 26716413, 2016). "DOCK3 was shown to promote invasion via RAC1 and is directly regulated by tumor-suppressive miRNAs such as miR-512-3p." (PMID 41200217, 2025). "At the single-cell level, DOCK3 was specifically enriched in malignant epithelial cluster 6, which was largely composed of tumor-derived cells and lacked expression of benign epithelial markers." (PMID 41200217, 2025).
tumor (continued). "Collectively, these findings indicated that DOCK3 functions not as a passive bystander but as a pivotal integrator of tumor progression signals and immune microenvironment remodeling." (PMID 41200217, 2025).
neurodegenerative disease (4 papers, 2013 to 2023). A disorder of the central nervous system characterized by gradual and progressive loss of neural tissue and neurologic function. "Newer, exciting drug screens for small molecule compounds that modulate DOCK3 conformational changes affecting DOCK3 and ELMO1 interactions have recently been published and could be explored for treating axonal injury and neurodegenerative diseases." (PMID 37895289, 2023). "Thus, stimulating downstream signaling of DOCK3 in combination with suppression of the ROCK/CRMP2 and ROCK/LIM kinase/cofilin pathways may be available for neurodegenerative diseases, such as glaucoma." (PMID 32973242, 2020).
neurodevelopmental disorder (3 papers, 2021 to 2025). A behavioral and cognitive disorder with onset during the developmental period that involves impaired or aberrant development of intellectual, motor, or social functions. "Further studies are necessary to better determine the prevalence of DOCK3-associated neurodevelopmental disorders and the frequency of non-CNS clinical manifestations in these patients." (PMID 37895289, 2023).
colorectal (1 paper, 2017). "DOCK3, also referred to as modifier of cell adhesion (MOCA), was also shown to be an inhibitor of Wnt/beta-catenin signaling, a pathway known to play an important role in colorectal carcinogenesis." (PMID 29228715, 2017).
retinopathy (1 paper, 2013). "Thus, the design of compounds capable of increasing the expression of Dock3 represents a novel strategy for the treatment of various forms of retinopathy." (PMID 23902942, 2013).
DOCK3 also shares sentences with these, for which no sentence is quoted: Cognitive impairment (28 papers); Stroke (27); dementia (19); depression (15); Hypertension (14); cognitive decline (13); diabetes (8); Anxiety (5); Parkinson disease (5); infection (4); coronary artery disease (3); schizophrenia (3); Atrophy (2); delirium (2); glioma (2); Hearing impairment (2); transient ischemic attack (2); type 2 diabetes (2); acne (1); adenoma (1); Apathy (1); apraxia (1); blepharospasm (1); Blindness (1); COVID-19 (1); developmental delay (1); Dyskinesia (1); endometriosis (1); heart failure (1); hippocampal atrophy (1).
A further 28 diseases each share a sentence with DOCK3 in 1 paper.